PDK1 (pyruvate dehydrogenase kinase 1)
Diseases named in the same sentence as PDK1 in open-access papers (continued):
Sharing a sentence is not in itself a finding about the gene and the disease.
cancer (continued). "Another example from cancer metabolism, is related to pyruvate dehydrogenase kinase 1 (PDHK1) which is also inducible by MYC and HIF-1α." (PMID 29257069, 2017). "PDK1 has been an emerging and promising target for anti-cancer therapies, which through both an Akt-dependent and independent manner is implicated in many aspects of carcinogenesis." (PMID 29064423, 2017). "The in-well kinase assay showed that the IC50 for DIC was 19.42 ± 0.032 μM, more than 150-fold lower than that for DCA (3.042 ± 0.087 mM), the most advanced PDK1 inhibitor in clinical trials for cancer therapy." (PMID 28617852, 2017). "Recently, there have been a number of reports showing that in some cancer cases PDK1 acts independently of the PI3K pathway to exert its oncogenic properties." (PMID 29064423, 2017). "MYC is a well-studied oncogene, with its respective protein being involved in the ability of cancer cells, as well as stem cells, to self-renew, and was lately proved to be PDK1-dependent in order to induce HEK cells transformation." (PMID 29064423, 2017). "PDK1 is an attractive target for cancer therapy due to its peculiar role in the regulation of cell motility, a fundamental process both in physiological and in pathological situations." (PMID 28287465, 2017). "Due to the great matter of attention drawn to PI3K and Akt as the major molecules in order to target many aspects of cancer, the role of PDK1 in cancer has been overlooked." (PMID 29064423, 2017). "In this study, we found that TCRP1 participates in cell transformation and cancer development through activation of PI3K/PDK1/AKT1 signaling." (PMID 28436990, 2017). "PDK1, the predominant isoform of PDKs in cancer cells, was recently identified as a potential target for anti-glycolytic therapy in cancer." (PMID 28761044, 2017). "As an essential molecule governing aerobic glycolysis that is upregulated in multiple human cancers, PDK1 has become a highly promising target for anticancer therapy." (PMID 28617852, 2017). "So far, few inhibitors of PDK1 have been in clinical trials for cancer treatment, potentially because only a limited number of PDK1 inhibitors are available." (PMID 28617852, 2017). "More importantly, we show that the 2-O-Bn-InsP5-mediated inhibition of PDK1/PLCγ1 complex assembly results in inhibition of cancer cell migration, invasion and in vivo dissemination using zebrafish xenotransplants." (PMID 27199173, 2016). "Our previous study demonstrated that the PDK1/PLCγ1 complex is required for cancer cell migration and invasion." (PMID 27199173, 2016). "Here we show that in cancer cells resistant to PI3Kα inhibition, PDK1 blockade restores sensitivity to these therapies." (PMID 27451907, 2016). "Previously, miR-375 was found to be significantly down-regulated in various types of cancers, suppressing core hallmarks of cancer by targeting several important oncogenes, such as PDK1, JAK2, AEG-1." (PMID 27036030, 2016). "Targeting either PDK1 or SGK1 restores the sensitivity of these resistant cancer cells to PI3Kα inhibition." (PMID 27451907, 2016). "Abnormal activation of the growth-factor-stimulated PI3K/PDK1/PKB signaling cascade is a common feature in cancer." (PMID 25742010, 2015). "Based on the published data, PDK1 seems to play a bigger role in regulating this process compared to its other isoforms, particularly in cancer cells." (PMID 25816777, 2015). "Reports have stated that PDK1 can promote cancer cell proliferation through PDK1-Akt/PKB-TSC2-MTORC1 signaling." (PMID 26318166, 2015). "The results indicated that YSC-ZDC inhibited proliferation of different cancer cell lines, downregulated phosphorylation of PDK1, and regulated Bcl-2 family proteins expression." (PMID 26089933, 2015). "Changes in the expression and activity of PDK1 and several AGC kinases have been linked to human diseases, including cancer." (PMID 26318166, 2015).
cancer (continued). "Given that PDK1 participates in the metabolic switch of the cancer cells, targeting PDK1 has become a novel therapeutic option in some cancers." (PMID 26398947, 2015). "Reduction of PDK1 by small interfering RNA (siRNA) in several cancer cells results in significant growth inhibition." (PMID 24925061, 2014). "Changes in the expression and activity of PDK1 and several AGC kinases have been linked to human disease, including cancer." (PMID 24739482, 2014). "Previous studies employing RNAi have provided evidence for a survival role for PDK-1 under hypoxic conditions as well as its importance in maintaining the glycolytic phenotype of cancer cells." (PMID 25404640, 2014). "PDK1 is induced by hypoxia in normal cell for adaptation to hypoxia and often expressed constantly in some cancer." (PMID 24506813, 2014). "There is accumulating evidence that PDK1 is overexpressed in particular cancer settings and activates cancer cell growth and survival independent of Akt signaling." (PMID 24739482, 2014). "Reduction of PDK1 by small interfering RNA (siRNA) in several cancer cells results in significant cell growth inhibition." (PMID 23867003, 2013). "The significant reduction of miR-375 in the PC samples and its inhibitory effect on the PDK1 oncogene prompted an investigation into its possible biological role in cancer cells." (PMID 24137444, 2013). "On the other hand, recent studies uncovered an AKT-independent signalling pathway in PIK3CA mutant cancer cell with low AKT activation that involved PDK1-dependent activation of SGK3." (PMID 23408974, 2013). "High expression of PDK1 has been detected in invasive cancers including lung and inhibition of PDK1 in several cancer cells results in significant cell growth inhibition." (PMID 23867003, 2013). "In cancer cells, PDK-1 is required for the conversion of pyruvate into lactate rather than acetyl-CoA, which occurs in the first step of the TCA cycle." (PMID 23135628, 2013). "A recent study demonstrated that DCA induces cancer cell apoptosis by selectively inhibiting PDK1 in cancer cells, leading to metabolic remodeling from glycolysis to glucose oxidation and normalization of mitochondrial function." (PMID 24212624, 2011). "Elevated PDK1 expression in cancer cells has been shown to result in reduced mitochondrial respiration and resistance to apoptosis." (PMID 21541279, 2011). "The Akt signaling pathway, from PI3K to phosphoinositide-dependent kinase-1 (PDK1) and from PDK1 to Akt, mediates apoptosis in human cancer cells." (PMID 20559509, 2010). "Several cancer cell lines from common types of cancer were analysed and they showed that PDK-1 expression was increased in hypoxia at both the mRNA and protein level in the majority." (PMID 18542064, 2008). "Further, inhibition of PDK-1 using antisense oligonucleotides decreased cell proliferation and increased apoptosis in cancer cells which expresses constitutively active PDK-1/AKT pathway." (PMID 17848913, 2007). "In contrast, PDK-1/AKT pathway is indispensable for the survival of cancer cell lines, such as RH30 and SMS-CTR." (PMID 17848913, 2007). "Given the limitations of DCA, we explored whether degrading PDK1 could be a more effective approach for cancer therapy." (PMID 40873633, 2025). "Furthermore, pyruvate dehydrogenase kinase-1 (PDK1), a mitochondrial enzyme frequently overexpressed in cancer cells, shifts glucose metabolism from oxidative phosphorylation to aerobic glycolysis." (PMID 40236700, 2025). "In conclusion, the KDM3A/METTL16/PDK1 axis plays an important role in cancer development and TKI resistance, which may offer new prognostic biomarkers and therapeutic targets for TKI resistance in the future." (PMID 42004224, 2025). "PDK1 promotes cancer metastasis due to its essential role in regulating cell migration." (PMID 41298573, 2025).
cancer (continued). "Additionally, the PDK1 protein was found to be enriched in the central carbon metabolism in cancer which is significantly altered in cancer cells to support their rapid proliferation, as well as survival." (PMID 40649898, 2025). "Pyruvate dehydrogenase kinase-1 (PDK1) is an enzyme involved in glycolysis that facilitates the transition from glucose oxidative metabolism to glycolytic metabolism in cancer cells by phosphorylating substrates and also reduces the damage caused by reactive oxygen species (ROS) accumulation." (PMID 39654890, 2024). "Thus, the enhanced activity of PDK-1 in cancer cells is the consequence of increased expression as well as post-translational modification." (PMID 38339256, 2024). "PDK is highly expressed in several cancers, which have four isoforms of PDK1-4." (PMID 38671369, 2024). "PDK1 is critically involved in regulating cancer cell growth, survival, metastasis and metabolism." (PMID 39578715, 2024). "PDK1 is involved in physiological processes, such as proliferation, metastasis, stress response, apoptosis, repair of DNA damage, and resistance to chemotherapy in cancer cells." (PMID 39242557, 2024). "Moreover, MiR-155-5p regulates the PDK1/mTOR pathway to inhibit LC3 but promote P62 protein expression in cancer cells, thus it further influences cellular autophagy activity." (PMID 38577616, 2024). "Furthermore, mass spectrometry proteomics analysis revealed a significant upregulation of PDK1 induced by high glucose in the Ishikawa cancer cell line." (PMID 38577616, 2024). "PDK1 is abnormally expressed in various cancers and is involved in cancer progression." (PMID 39578715, 2024). "Besides epidermal self-renewal, integrin-mediated YAP activation via the FAK/Src and PI3K/pyruvate dehydrogenase kinase 1 (PDK1) pathways is involved in wound healing and cancer progression." (PMID 39684613, 2024). "Several studies have shown that EGFR and PDK1 interact reciprocally, promoting cancer development." (PMID 38689087, 2024). "Recent data indicated that PDK1 expression is dysregulated in multiple cancer types." (PMID 39242557, 2024). "In cancer cells, ubiquitination of PDK1 leads to its proteasomal degradation, suggesting that the ubiquitin-proteasome system may regulate PDK1 levels in skeletal muscle." (PMID 39080182, 2024). "In contrast, many AKT and PDK1 inhibitors are being tested in cancer clinical trials." (PMID 37531320, 2023). "Castel and colleagues reported that inhibition of PDK1 sensitizes cancer cells to PI3K blockade." (PMID 37531320, 2023). "As a result, PDK1 has emerged as a highly promising target for cancer therapy." (PMID 38035024, 2023). "Moreover, Klotho inhibits autophagy, inhibits glycolysis (via hexokinase/HK, phosphofructokinase 1/PFK1, PK M2, and PDK1), fatty acid synthesis, and purine metabolism—some specific to cancer cell effects—making it a promising drug target candidate." (PMID 37109525, 2023). "Indeed, there are drugs already approved for human use and in clinical development directed at growth factor receptors, PI3K and Akt (also known as protein kinase B; PKB), the best characterized anti-cancer target downstream of PDK1." (PMID 37311034, 2023). "It has been reported that combined PI3K and PDK1 blockade is highly effective in blocking cancer cell growth, which may provide an improved therapeutic approach to treat cancers." (PMID 37531320, 2023). "Importantly, our data further demonstrated that PDK1 expression was critical for FOXM1‐mediated cancer growth in vitro and in vivo." (PMID 35656815, 2022). "Importantly, PDK1 has also been evaluated to promote cancer stem cell initiation and maintenance through the phosphorylation and regulation of PLK1/Myc proto-oncogene protein (MYC) pathway." (PMID 35318320, 2022). "Therefore, genetically or chemically targeting of PDK1 would result in decreased energy availability, leading to cancer cell death." (PMID 36340043, 2022).
cancer (continued). "In different cancers, the upregulation of PDK1 (pyruvate dehydrogenase kinase 1) minimizes the PDH (pyruvate dehydrogenase) activity via the induction of its E1α subunit (PDHA1) phosphorylation and, subsequently, turns the energy metabolism from oxidative phosphorylation to aerobic glycolysis." (PMID 36144705, 2022). "Recently, PDK1 was reported as an oncogene in various cancers." (PMID 35961973, 2022). "PDK1 is therefore a good target for cancer therapies, for which inhibitors have been tested." (PMID 36551928, 2022). "This releases TNS2 from its binding partner IRS-1, which in turn upregulates Glut4 and PDK1, enzymes that may play a critical role in the glucose metabolism of cancer cells." (PMID 35804982, 2022). "A majority of cuproptosis-related genes like CP, MT1E, MT1F, MT1X, VEGFA, and PDK1 were expressed significantly higher on cancer cells, indicating that cuproptosis might occur mainly on cancer cells." (PMID 36211378, 2022). "We speculate that this is because HNK reduces the expression of HIF-1α protein, which in turn inhibits the transcription of key molecules GLUT1, HK2, and PDK1 on the glycolysis link, resulting in a decrease in the glycolysis level of cancer cells." (PMID 35350760, 2022). "We therefore assessed whether effects of DCA on PDK1 in the differentiated L6 skeletal muscle cells (myotubes) mimic those in cancer cells." (PMID 34445316, 2021). "Studies have indicated that PDK1 is indirectly regulated by miRNAs in various cancers." (PMID 34298795, 2021). "PDK1 targeting miRNAs have been reported in other cancers as well." (PMID 34298795, 2021). "Thus far, knocking down ARNT has been shown to suppress the expression of PDK1 (pyruvate dehydrogenase kinase in certain cancers." (PMID 34179020, 2021). "In this review, we describe that these polyphenols can alter the function of multiple molecules effective in PI3K signaling, such as Akt, mTOR, PTEN, and PDK-1, through different mechanisms, avoiding cancer progression, drug resistance, angiogenesis, and metastasis." (PMID 34744708, 2021). "Moreover, several reports show that PDK1 is implicated in Ras/MAPK and Myc signaling pathways, which are frequently altered in cancer." (PMID 34789718, 2021). "PDK1 reduces the rate of TCA cycle to prevent ROS accumulation in hypoxic cancer cells." (PMID 34359884, 2021). "In hypoxia and cancer, HIF1α activates the expression of PDK1 and PDK3." (PMID 33739396, 2021). "For instance, GLUT1 inhibitors (e.g., Ritonavir, Fasentin), hexokinase inhibitors (e.g., Ionidamine, 3-BrPA), PKM2 inhibitors (e.g., OA, TT-232, VK3, VK5), and PDK1 inhibitor (DCA) are metabolic inhibitors that have been evaluated in a variety of cancer types with Warburg phenotype." (PMID 34948229, 2021). "Thus, the effects of TMEM116 on cancer cell proliferation, clone formation, migration, and invasion are mainly mediated through PDK1." (PMID 34789718, 2021). "Emerging evidence indicates that targeting PDK1 may represent an efficient strategy against various cancers." (PMID 34298795, 2021). "Interestingly, the phosphoinositide 3‐kinase (PI3K)/AKT/mTOR signal pathway, one of the most commonly deregulated pathways in human cancers, has been verified to be modulated by PDK1 and VEGFA." (PMID 34431227, 2021). "Although PDK1 has been demonstrated as an “un-regulable” kinase because of the auto-phosphorylation and activation mechanism, the genetic amplification of PDK1 in diverse cancers has been considered to promote PDK1 oncogenic functions." (PMID 34353330, 2021). "Recently, accumulating evidence shows that the increased PDK1 protein abundance induced by the genomic amplification robustly contributes to its oncogenic functions in promoting tumorigenesis in different types of cancers." (PMID 34353330, 2021). "PDK1 has emerged as an important oncogene in many types of cancers including PC." (PMID 34221996, 2021).
cancer (continued). "Although the genomic amplification of PDK1 has been established in many cancers, the mutations, especially driver mutations for PDK1 are not well evaluated." (PMID 34353330, 2021). "The inhibition of PDK1 not only inhibits the glycolytic profile of cancer cells, but its downregulation may also be responsible for the enhancement of the spare respiratory capacity observed in uPAR KO cancer cells." (PMID 32012858, 2020). "Additionally, glucose regulated protein 78 (GRP78) interacts with α2-macroglobulin to activate AKT1 via PDK1, as well as mTOR to enhance cancer cell proliferation and radiotherapy resistance in GBM." (PMID 32333246, 2020). "The prognostic performance of PDK1 varied among different cancers." (PMID 33221755, 2020). "Whether ZnO-NPs inhibit the activation of p70S6K through ERK and/or PDK1 signaling pathways with their anti-cancer property requires further investigation." (PMID 32111101, 2020). "Accumulating data demonstrate that overexpression of PDK1 can occur in various cancers." (PMID 32503307, 2020). "Despite, a similar role of both DRP1 and PDK1 in promoting certain cancer phenotypes and fueling Warburg effect, the physiological crosstalk between these proteins is completely unknown." (PMID 33738242, 2020). "Monoubiquitination of PDK1 in cancer cell lines can be reversed by USP4 catalyzation, the function of which still remains unclear." (PMID 33004065, 2020). "In many cancers, highly expressed pyruvate dehydrogenase kinase 1 (PDK1) reduces the activity of pyruvate dehydrogenase (PDH) by inducing the phosphorylation of its E1α subunit (PDHA1) and subsequently, shifts the energy metabolism from OxPhos to aerobic glycolysis." (PMID 32825675, 2020). "Pyruvate dehydrogenase kinase 1 (PDK1) was known as a critical regulator in cancer metabolism." (PMID 33029299, 2020). "Indeed, recent studies have highlighted the significance of PDK1 inhibition to increase the efficacy of other therapies on some cancer models." (PMID 33266219, 2020). "HIF-1α may upregulate PDK1, which promotes PGC-1α activity to reduce cancer cell damage caused by ROS accumulation." (PMID 33266219, 2020). "Moreover, PDK1 was revealed as a key executor of LIN28-driven proliferation of cancer cells through direct potentiation of cellular metabolism." (PMID 32560271, 2020). "Moreover, higher PDK1 immunoreactivity was observed in metastatic foci than the corresponding primary carcinomas (P = 0.02, lower left)." (PMID 32071289, 2020). "PDK1 is the master regulator of at least 23 other AGC kinases whose downstream signaling has often been implicated in various diseases and particularly in cancer." (PMID 30622697, 2019). "Accumulating evidences demonstrated that PDK1 is a promising therapeutic target and suggested that PDK1 inhibitors may be a valuable tool to prevent cancer progression and metastasis." (PMID 31139017, 2019). "Abnormal signaling of the PDK1 pathway has been shown in different cancers." (PMID 31139017, 2019). "Our data further suggest that combination of PDK1 inhibitors with selective PI3K inhibitors might enhance their anti-cancer activity, possibly by targeting SGK3-dependent resistance mechanisms." (PMID 31088502, 2019). "Our study indicated that PDK-1 silence promoted cancer cell apoptosis and caspase-3 activity." (PMID 30988063, 2019). "In summary, we demonstrate that PDK-1 knockdown induced cancer cell apoptosis may be through Hippo–YAP/IRS2 signal pathway." (PMID 30988063, 2019). "SA16 and IB35 are novel dual inhibitors that could block both PDK1 and Aurora A, which are activated in several cancers." (PMID 31683659, 2019). "Overexpression IRS2 mitigated PDK-1 silence induced cancer cell apoptosis." (PMID 30988063, 2019). "PDK1 inhibition impairs cell growth and increases cell death under hypoxia in cancer." (PMID 31011292, 2019). "PDK1 itself has been recognized to have an important role in cancer." (PMID 30622697, 2019).